EZH2 (enhancer of zeste 2 polycomb repressive complex 2 subunit)
Diseases named in the same sentence as EZH2 in open-access papers (continued):
Sharing a sentence is not in itself a finding about the gene and the disease.
endometrial cancer (continued). "Moreover, EZH2 silencing enhanced the cytotoxicity of cisplatin and taxanes in HEC1A and Ishikawa endometrial cancer cell lines." (PMID 36230683, 2022). "As endometrial cancer in Ptend/d mice does not substantially affect the viability up through five months of age, current results suggest that deletion of Ezh2 negatively impacts the disease outcome." (PMID 35269532, 2022). "To determine the impact of Ezh2 deletion on the development and progression of endometrial cancer induced by PTEN inactivation, we generated mice containing double deletion of Ezh2 and Pten using Cre recombinase driven by the progesterone receptor (Pgr) promoter." (PMID 35269532, 2022). "MiR-449a suppressed the growth and metastasis of endometrial cancer by directly targeting the NDRG1 gene and miR-26a promoted invasion/metastasis by inhibiting PTEN and inhibited cell proliferation by repressing EZH2 in HCC." (PMID 33681289, 2021). "Although previous studies have examined EZH2 expression in endometrial cancer, there has been no comprehensive analysis of EZH2 expression and function in endometrial cancer using EZH2-selective inhibitors." (PMID 28418882, 2017). "Significantly elevated expression of EZH2 was detected in endometrial cancer cell lines compared with that in EICs (non-tumor control)." (PMID 28418882, 2017). "MicroRNA-101 targets EZH2, MCL-1 and FOS to suppress proliferation, invasion and stem cell-like phenotype of aggressive endometrial cancer cells; MicroRNA-101 inhibits cell progression and increases paclitaxel sensitivity by suppressing MCL-1 expression in human triple-negative breast cancer." (PMID 32309578, 2016). "A recent report that investigated the expression of CBX2 in human cancers showed initial evidence of an oncogenic role; however, the overexpression of both CBX2 and EZH2 in the basal-like subgroup indicates the importance of interplay between PRC1 and PRC2 in endometrial cancer." (PMID 26431491, 2015). "Subgroup analysis revealed that high EZH2 expression might predict poor OS in NSCLC, endometrial carcinoma, and oral tongue carcinoma, as well as poor DFS in renal cell carcinoma." (PMID 25974088, 2015). "The present study showed that EZH2 was overexpressed in complex hyperplasia, atypical hyperplasia and endometrial cancer, but not in simple hyperplasia and normal endometrium." (PMID 25295088, 2014). "In non-UCS related endometrial cancers, overexpression of EZH2 is well established." (PMID 38146588, 2023). "No clinical trials of EZH2 inhibitors in endometrial cancer have been reported." (PMID 35269532, 2022). "On the other hand, silencing EZH2 histone methyltransferase downregulates the TSLP expression in oesophagus squamous cell carcinoma cells, which supports our observation that histone methylation regulated sfTSLP transcription in KLE human endometrial cancer cells." (PMID 33652749, 2021). "However, neither significant ERα expression nor a significant effect of estrogen on EZH2 expression was observed in the endometrial cancer cell lines in this study." (PMID 28418882, 2017). "Further studies relevant to the non-established roles of EZH2 in endometrial cancer are warranted." (PMID 28418882, 2017). "Furthermore, the 5-year survival rates of low and highly EZH2 expressing endometrial cancers were 80% and 56% respectively, and were independent of other known prognostic factors such as histologic type, grade, vascular invasion, depth of myometrial infiltration, and clinical FIGO stage." (PMID 33050946, 2020). "However, the role of EZH2 in endometrial cancer has not been fully determined." (PMID 25295088, 2014). "The differential expression of EZH2 in stage IA, IB and IC endometrial cancer was not significantly different and indicated that it is more important in the discrimination of early-stage endometrial cancer than advanced endometrial cancer (stage II, III and IV)." (PMID 25295088, 2014).
endometrial cancer (continued). "Collectively, these studies identified potential contributing factors to the unfavorable outcome of endometrial cancer lacking both PTEN and EZH2." (PMID 35269532, 2022).
triple-negative breast carcinoma (67 papers, 2012 to 2026). An invasive breast carcinoma which is negative for expression of estrogen receptor (ER), progesterone receptor (PR), and human epidermal growth factor receptor 2 (HER2). "Enhancer of zeste homolog 2 (EZH2) has been associated with poor prognosis in triple negative breast cancer (TNBC)." (PMID 36446780, 2022). "We found that stable silencing of MUC1-C in BT-549 triple-negative breast cancer (TNBC) cells is associated with downregulation of EZH2 mRNA levels." (PMID 28785086, 2017). "In summary, our study demonstrates that EZH2 overexpression is significantly associated with high grade triple-negative breast carcinoma as well as corresponding DCIS, plus many high-grade HER2-positive breast carcinomas." (PMID 27113214, 2016). "There are studies suggesting that EZH2 probably plays an important role in carcinogenesis of breast carcinoma, and high expression of EZH2 was associated with triple-negative breast carcinoma." (PMID 27113214, 2016). "Our study suggests that EZH2 overexpression is an immunophenotypic feature of high-grade and highly proliferative triple-negative breast carcinoma and is independently associated with a high proliferative index and HER2 positivity." (PMID 27113214, 2016). "Furthermore, EZH2 has been shown to interact with NFκB, resulting in the activation of genes associated with triple-negative breast cancer." (PMID 39516467, 2024). "In the present study, we found that EZH2 was significantly overexpressed in triple- negative breast carcinoma and was associated with high tumor cell proliferation, whereas low grade ER-positive breast carcinoma such as tubular carcinoma and mucinous carcinoma showed low EZH2 expression levels." (PMID 27113214, 2016). "Based on these findings, we propose that EZH2 likely acts as a key driver in the pathogenesis and progression of triple-negative breast cancer by modulating cell cycle progression." (PMID 41607539, 2026). "Overexpression of EZH2 and H3K27me3 levels has been shown to induce peritoneal metastasis in triple-negative breast cancer models." (PMID 40042761, 2025). "Because depletion of EZH2 suppressed ER-negative tumor growth and metastasis in preclinical models, EZH2 has emerged as a potential therapeutic target for triple-negative breast cancer (TNBC)." (PMID 35137163, 2022). "EZH2 is overexpressed in multiple types of cancer including triple-negative breast cancer (TNBC), and high expression levels correlate with poor prognosis." (PMID 34195095, 2021). "In EZH2-dependent triple-negative breast cancer cells, the newly developed EZH2 specific degrader MS1943 reduced cell proliferation and induced apoptosis effectively in contrast to selective inhibitors of the enzymatic activity of EZH2." (PMID 35008205, 2021). "In clinical samples, JMJD6 and EZH2 expression significantly correlated in both normal and tumor samples, however the strongest correlation was observed in triple-negative breast cancer (TNBC) subtype." (PMID 33246425, 2020). "Phosphorylation of EZH2 at T416 promotes its ability to induce triple-negative breast cancer cell migration, invasion and tumor formation in vitro and in vivo." (PMID 31973032, 2020). "EZH2 overexpression in triple-negative breast cancer cells was shown to be related to self-renewal, migration, invasion, and tumour suppressor silencing." (PMID 29853899, 2018). "This was further supported by a study from our group, which showed that EZH2 and RelA localized to the RelB promoter and supported transcription of RelB in triple-negative breast cancer cells." (PMID 29874793, 2018).
triple-negative breast carcinoma (continued). "Some studies have reported that nuclear factor-κB (NF-κB) activation is critical for cytokines expression and dependent upon high EZH2 expression in triple-negative breast cancer cells." (PMID 30578411, 2018). "Upon hypoxia, active HIF-1α results in inactivation of PRC2 and release of EZH2, leading to functional switch to EZH2/Forkhead box M1 (FoxM1) complex-induced expression of MMPs and invasion in triple-negative breast cancer." (PMID 28561778, 2017). "EZH2 knockdown inhibits the onset and growth of xenografts derived from triple-negative breast cancer, and the opposite phenotype emerges when EZH2 is overexpressed." (PMID 26349457, 2016). "Compared with normal or benign hyperplastic lobules and ducts, EZH2 expression was elevated in high-grade DCIS adjacent to triple-negative breast carcinoma (0 versus 90 %, p < 0.001)." (PMID 27113214, 2016). "ER-positive breast carcinoma with low proliferative index (Ki67 < 14 %) showed the lowest expression and triple-negative breast carcinoma showed the highest overexpression of EZH2, 18.5 % (10/54) versus 90.9 % (50/55) (Chi-square, p < 0.001)." (PMID 27113214, 2016). "Our data identifies an HMT-independent role of EZH2 as a transcriptional activator of RelB in TNBC contributing to the maintenance of triple-negative breast cancer TICs." (PMID 27764181, 2016). "Strong overexpression of EZH2 with a score of 9 was observed in high grade triple-negative breast carcinoma." (PMID 27113214, 2016). "In this regard, activities of the NF-κB transcription factor family as well as activities of the histone methyltransferase EZH2 have been shown to be important in self-renewal of triple-negative breast cancer (TNBC)." (PMID 27764181, 2016). "Our finding of high overexpression of EZH2 in triple-negative DCIS as well as invasive breast carcinoma supports an important role of EZH2 in carcinogenesis of triple-negative breast carcinoma." (PMID 27113214, 2016). "Perhaps the next step is to assess the utility of EZH2 inhibitors in EZH2-overexpressing triple-negative breast carcinomas." (PMID 27113214, 2016). "EZH2 is a promising target for prognostication and treatment in the aggressive and otherwise unresponsive triple-negative breast carcinomas." (PMID 27113214, 2016). "We report that gene expression and inhibition of triple negative breast cancer cell growth (MDA-MB-231) are markedly increased when targeting both EZH2 and EHMT2, either by siRNA knockdown or pharmacological inhibition, rather than either enzyme independently." (PMID 26300989, 2015). "Our findings suggest that OLFML2A may facilitate cell cycle progression by regulating EZH2, implicating it as a potential therapeutic target for triple-negative breast cancer." (PMID 41607539, 2026). "In triple-negative breast cancer cells, there is a subpopulation of cells with high EZH2 expression that exhibit increased mammosphere formation and metastatic potential, and inhibition of EZH2 reduces mammosphere size and abundance." (PMID 39409910, 2024). "Furthermore, it has been declared that if reducing EZH2 expression in triple-negative breast cancer cells, DLC1 expression is elevated and curcumin-induced inhibition of cancer growth is facilitated." (PMID 35414117, 2022). "Interestingly, inconsistent with the general results of EZH2 for triple-negative breast cancer, we found that patients with lower EZH2 expression had significantly shorter overall survival than those with higher EZH2 expression in TNBC patients." (PMID 35813302, 2022). "In addition, it has been documented that β-catenin can activate EZH2 expression through synergistic interactions with HMGA2 in triple-negative breast cancer." (PMID 33823894, 2021). "EZH2 phosphorylation by CDK2 promotes progression of triple-negative breast cancer (TNBC)." (PMID 31704972, 2019).
triple-negative breast carcinoma (continued). "Interestingly, EZH2 was also found to support NF-κB target gene expression in triple-negative breast cancer cells by acting as a coactivator in a complex containing RelA and RelB." (PMID 29874793, 2018). "As this study demonstrates that EZH2 is consistently overexpressed in high grade triple-negative breast carcinoma, we hypothesize that EZH2 plays an important role in tumorigenesis for this unique breast carcinoma." (PMID 27113214, 2016). "In summary, triple-negative breast carcinoma showed the highest overexpression of EZH2." (PMID 27113214, 2016). "ER-positive breast carcinoma with a low proliferative index showed the lowest percentage of EZH2 overexpression, whereas triple-negative breast carcinoma showed the highest percentage of EZH2 overexpression, 18.5 % (10/54) versus 90.9 % (50/55), (Chi-square, p < 0.001)." (PMID 27113214, 2016). "For example, two SNPs (rs6950683 and re3757441) of EZH2 coding for the histone methyltransferase that causes the trimethylation of H1K26 and, consequently, suppresses the cancer preventive genes were shown to be associated with a tumor size in triple-negative breast cancer." (PMID 37175659, 2023). "Moreover, we showed that EZH2 overexpression rescued CUL1 knockdown-decreased transcriptional activities of NF-κB, which is accordant with previous findings that NF-κB activation is critical for cytokines expression and dependent upon high EZH2 expression in triple-negative breast cancer cells." (PMID 30578411, 2018). "Collectively, these results establish EZH2 as a downstream interacting partner of OLFML2A and suggest that its expression is positively regulated by OLFML2A in triple-negative breast cancer (TNBC) cells." (PMID 41607539, 2026). "For instance, EZH2- and PKM2-mediated co-silencing of SLC16A9 in triple-negative breast cancer (TNBC) induces a metabolic shift from glycolysis to fatty acid oxidation, highlighting potential for synthetic lethality via dual-targeting strategies." (PMID 40842995, 2025). "Although little is known about the mechanistic aspects of EZH2 activity in GBM, the inhibition of EZH2 expression by miR-340 in triple negative breast cancer has led to decreased levels of miR-21, revealing a key miRNA network pathway." (PMID 36984801, 2023). "EZH2 inhibits the transcription of TIMP2, which boosts activities of MMP-2 and MMP-9, which in turn increases the invasive activity of triple-negative breast cancer cells." (PMID 35912155, 2022). "Released EZH2 participates in the EZH2/Forkhead box M1 (FoxM1) complex and induces MMP expression and invasion in triple-negative breast cancer (TNBC)." (PMID 29556394, 2018). "The effects on gene expression of the selective EZH2 inhibitor GSK343 and the selective EHMT2 inhibitor UNC0638 used alone or in combination were also examined using the MDA-MB-231 triple negative breast cancer cell line." (PMID 26300989, 2015). "Additionally, the upregulation of EZH2, as a downstream target of the MEK/ERK/Elk signaling pathway, correlates with invasion, proliferation, and poor prognosis in triple-negative breast cancer." (PMID 40042761, 2025). "Notably, EZH2 and NSD2 expression were coordinately higher in triple-negative breast cancer (TNBC) than that in other subtypes." (PMID 33665162, 2020). "Since EZH2 promotes RelB production and tumor initiating cells in triple-negative breast cancer, it is interesting to consider what effects NIK stabilization may have on EZH2-RelB crossregulation." (PMID 29874793, 2018).
triple-negative breast carcinoma (continued). "Here we show that EZH2, through a methyltransferase-independent mechanism, promotes the transcriptional activation of the non-canonical NF-κB subunit RelB to drive self-renewal and the TIC phenotype of triple-negative breast cancer cells." (PMID 27764181, 2016). "Enhancer of zeste homolog 2 (EZH2), the catalytic subunit of the polycomb repressive complex 2 (PRC2), which mediates transcriptional repression through histone H3 lysine 27 trimethylation (H3K27me3), is highly expressed in aggressive triple-negative breast cancer (TNBC)." (PMID 41413688, 2025). "EZH2, a driver of invasiveness in multiple cancer types, upregulates KRT14 through the H3K27me3 mechanism to enhance peritoneal metastasis in triple-negative breast cancer (TNBC), suggesting that targeted inhibition of EZH2 could potentially impede TNBC metastasis." (PMID 39043634, 2024). "In addition, strongly positive EZH2 scores correlated with the lack of Her2 overexpression (p = 0.004) and triple negative breast carcinomas (p = 0.0014)." (PMID 23133536, 2012). "Thus, inhibiting EZH2 function may be relevant for treatment of triple-negative breast carcinoma, which currently has no targeted, effective therapy." (PMID 27113214, 2016). "Intriguingly, we observed that EZH2 was strongly overexpressed in high-grade DCIS adjacent to triple-negative breast carcinoma, whereas UDH in benign lesions did not overexpress EZH2." (PMID 27113214, 2016). "Forth, we could not assess EZH2 expression in this study according to subtype (luminal A, luminal B, luminal HER2, HER2-type and triple-negative breast cancer) due to sample limitation." (PMID 28241804, 2017). "In addition to the previous report that integrin α6β1-activated FAK induces GLI-1 expression in triple-negative breast cancer, our present results with ITGA11 KD demonstrated that integrin α11 induced activation (nuclear translocation) of GLI-1, but not HIF1α and EZH2." (PMID 38664825, 2024).